HTRA1 (HtrA serine peptidase 1)
Diseases named in the same sentence as HTRA1 in open-access papers (continued):
Sharing a sentence is not in itself a finding about the gene and the disease.
esophageal cancer (3 papers, 2012 to 2018). A primary or metastatic malignant neoplasm involving the esophagus. "HtrA1 protein expression is associated with the occurrence and development of esophageal cancer." (PMID 22935172, 2012). "HtrA1 expression is associated with the occurrence and development of esophageal cancer." (PMID 22935172, 2012). "Yu and colleagues explored the possible involvement of HtrA1 levels in cell invasiveness, differentiation, stage and metastasis formation in esophageal cancer tissue and adjacent normal-appearing tissue from 63 patients." (PMID 26035313, 2015). "The purposes of this study were to measure both the mRNA and protein expression levels of high-temperature requirement serine peptidase 1 (HtrA1) in human esophageal cancer tissues and their adjacent, comparatively normal esophageal tissues." (PMID 22935172, 2012). "This study utilized semi-quantitative RT-PCR (reverse transcription-polymerase chain reaction) and Western blotting to measure HtrA1 mRNA and protein expression in human esophageal cancer tissues and their adjacent normal esophageal tissues." (PMID 22935172, 2012). "The percentage of positive HtrA1 expression in human esophageal cancer tissues and their adjacent normal esophageal tissues was 42.86% and 68.25%, respectively." (PMID 22935172, 2012). "HtrA1 mRNA expression in the esophageal cancer tissues was significantly lower than in their adjacent normal esophageal tissue (p < 0.05)." (PMID 22935172, 2012). "HtrA1 protein expression in esophageal cancer was significantly lower than that in adjacent normal esophageal tissues." (PMID 22935172, 2012). "Subsequent changes in the invasiveness of Eca-109 cells were observed, and the relationship between HtrA1 protein expression and the occurrence, development and metastasis of human esophageal cancer was explored." (PMID 22935172, 2012). "In the present study, we showed that the percentages of positive HtrA1 expression in human esophageal cancer tissues and their adjacent normal tissues were 42.86% and 68.25%, respectively." (PMID 22935172, 2012). "The clinical and pathological correlation between HtrA1 expression levels and the occurrence and development of esophageal cancer was analyzed." (PMID 22935172, 2012). "Western blot analysis revealed that HtrA1 protein expression in esophageal cancer tissue was significantly lower than in the adjacent normal esophageal tissue (p < 0.05)." (PMID 22935172, 2012). "We also used RNA interference or transfected an HtrA1 recombinant plasmid to downregulate or overexpress the HtrA1 protein in the Eca-109 human esophageal cancer cell line." (PMID 22935172, 2012). "The expression levels of HtrA1 mRNA and protein in esophageal carcinoma were significantly lower than the levels expressed in their adjacent normal esophageal tissue (p < 0.05)." (PMID 22935172, 2012). "HtrA1 participates in the invasion and metastasis of esophageal cancer cells." (PMID 22935172, 2012). "Also, HtrA1 mRNA and protein expression levels in esophageal carcinoma were significantly lower than in the adjacent normal esophageal tissue (p <0.05)." (PMID 22935172, 2012). "In the future, HtrA1 may be a potential target for the treatment of esophageal cancer." (PMID 22935172, 2012). "The expression of HtrA1 in human esophageal cancer tissues, as well as its relevance in the occurrence and development of esophageal cancers, has not yet been reported." (PMID 22935172, 2012). "Also, there have been no reports correlating HtrA1 expression with esophageal cancer cell metastasis." (PMID 22935172, 2012).
keloid (3 papers, 2018 to 2025). An irregularly shaped, elevated mark on the skin caused by deposits of excessive amounts of collagen during wound healing. "Consistent with this notion, we found HtrA1-knockdown inhibited the proliferation of keloid fibroblasts, and that recombinant HtrA1 added to the culture medium stimulated the proliferation of keloid fibroblasts." (PMID 29695130, 2018). "In all keloid tissue samples from four patients, HtrA1 protein was up-regulated, relative to four normal skin samples." (PMID 29695130, 2018). "Taken together, these observations suggest that HtrA1 contributes to the development of keloid lesions as matrix protease by remodelling keloid-specific ECM or cell surface molecules." (PMID 29695130, 2018). "The proportion of HtrA1-positive cells in keloids was significantly higher than that in normal skin, and HtrA1 protein was up-regulated relative to normal skin." (PMID 29695130, 2018). "We examined the expression and localization of HtrA1 in keloid tissues, using in situ hybridization and immunohistochemical studies." (PMID 29695130, 2018). "The proportion of HtrA1-positive cells was significantly higher in keloids than in normal skin (p < 0.001)." (PMID 29695130, 2018). "In summary, the expression of HtrA1 was revealed, especially in keloid active lesions, and the silencing of HtrA1 suppressed the proliferation of keloid fibroblasts." (PMID 29695130, 2018). "We have previously analysed the gene expression profiles in keloid tissue and found that HtrA1 was markedly up-regulated in the keloid lesions." (PMID 29695130, 2018). "Enumeration of HtrA1-positive cells after immunohistochemical staining indicated that the proportion of cells expressing detectable levels of HtrA1 in keloid tissue ranged from 12.4% to 48.4%, with an average of 31.9 ± 10.5%." (PMID 29695130, 2018). "HtrA1 mRNA was strongly up-regulated, and expression of HtrA1 was more pronounced in keloid lesions." (PMID 29695130, 2018). "We propose that HtrA1 functions as a matrix protease that stimulates keloid development because the keloid matrix consists mainly of collagens, fibronectin, and proteoglycans, which are substrates for HtrA1." (PMID 29695130, 2018). "HtrA1 was highly expressed in keloid tissues, and the suppression of the HtrA1 gene inhibited the proliferation of keloid-derived fibroblasts." (PMID 29695130, 2018). "Matrix protein fragments produced by HtrA1 may activate keloid cells, leading to further progression of the disease." (PMID 29695130, 2018). "HtrA1 may promote keloid development by accelerating cell proliferation and remodelling keloid-specific extracellular matrix or cell surface molecules." (PMID 29695130, 2018). "We propose that HtrA1 may be a pivotal molecule in keloid pathogenesis, and our discussion centres on the possible roles of HtrA1 in the molecular mechanism of keloid development." (PMID 29695130, 2018). "HtrA1 is suggested to have an important role in keloid pathogenesis." (PMID 29695130, 2018). "HtrA1 may facilitate keloid pathogenesis through the activation of TGF-β1 mediated by LTBP-1 cleavage." (PMID 29695130, 2018). "We analysed HtrA1 localization and its role in keloid pathogenesis." (PMID 29695130, 2018). "To investigate role of HtrA1 in keloid pathogenesis, we examined whether HtrA1 affects cell proliferation by silencing HtrA1 gene expression using specific small interfering RNA (siRNA)." (PMID 29695130, 2018). "Therefore, HtrA1 was strongly up-regulated at the protein level in active areas of the keloid lesions." (PMID 29695130, 2018). "Fibroblast-like cells expressed more HtrA1 in active keloid lesions than in surrounding lesions." (PMID 29695130, 2018). "To confirm the up-regulation of the mRNA level for HtrA1, we previously observed using microarray and Northern blot analyses, and to determine the localization of HtrA1 mRNA in keloid lesions, in situ hybridization was performed using skin samples from six keloid patients." (PMID 29695130, 2018).
keloid (continued). "HtrA1 may degrade keloid matrix and accelerate ECM remodelling in keloid lesions." (PMID 29695130, 2018). "HtrA1 may be useful as a target of keloid treatment, although further study is required." (PMID 29695130, 2018). "The addition of HtrA1 stimulated the proliferation of keloid fibroblasts, but not normal fibroblasts." (PMID 29695130, 2018). "Moreover, the addition of recombinant HtrA1 in culture medium stimulated the proliferation of keloid fibroblasts but not normal fibroblasts." (PMID 29695130, 2018). "Interestingly, the inhibition or stimulation of proliferation with silencing or additional HtrA1 was clearly demonstrated in keloid fibroblasts, but not in normal fibroblasts." (PMID 29695130, 2018).
Obesity (3 papers, 2017 to 2022). Accumulation of substantial excess body fat. "NOX4, CCDC80, COL1A2, HTRA1, and KLHL29 were identified as key genes by LASSO regression analysis, among which HTRA1 and KLHL29 showed a close association with immune system infiltration in DCM and obesity." (PMID 36547458, 2022). "The key genes KLHL29 and HTRA1 may play critical roles in obesity-related DCM." (PMID 36547458, 2022). "The key genes, NOX4, CCDC80, COL1A2, HTRA1, and KLHL29 were significantly expressed in DCM, with KLHL29 and HTRA1 especially closely associated with the immune response, which might be markers for obesity-induced DCM and be potential avenues for exploration in immunotherapy." (PMID 36547458, 2022).
Parkinson disease (3 papers, 2019 to 2025). A progressive degenerative disorder of the central nervous system characterized by loss of dopamine producing neurons in the substantia nigra and the presence of Lewy bodies in the substantia nigra and locus coeruleus. "Several implicated host proteins—notably HTRA1, MAPT, and RAB6A—are highly expressed in the cerebellum and basal ganglia, aligning with observed clinical features such as ataxia, opsoclonus‐myoclonus, and parkinsonism." (PMID 40259581, 2025). "Interestingly, pathway enrichment analysis of RNA-seq data of HtrA1 Tg mice showed two significant enriched pathways, ~ HOXD1 and Parkinson’s disease, that are evidently related to angiogenesis as discussed." (PMID 36142120, 2022).
periodontitis (3 papers, 2014 to 2024). An acute or chronic inflammatory process that affects the tissues that surround and support the teeth. "The increase of HtrA1 immunostaining in the epithelial superficial layer associated with increasingly severe forms of periodontitis appears to confirm the correlation between HtrA1 expression and the altered periodontal environment." (PMID 24979214, 2014). "Perhaps, more interestingly, HTRA1 has been found to play a role in gingivitis and aggressive periodontitis." (PMID 27088090, 2016). "An essential feature found in chronic and aggressive periodontitis is the strong HtrA1 positivity in the epithelium, higher than in the epithelial layers of healthy and gingivitis specimens." (PMID 24979214, 2014). "The aim of this study was to investigate for the first time if HtrA1 has a role in gingivitis and in generalized forms of chronic and aggressive periodontitis." (PMID 24979214, 2014). "Expression of HtrA1 was investigated in 16 clinically healthy gingiva, 16 gingivitis, 14 generalized chronic periodontitis and 10 generalized aggressive periodontitis by immunohistochemistry and real-time PCR." (PMID 24979214, 2014). "In chronic and aggressive periodontitis we observed HtrA1 immunostaining in the whole thickness of the epithelium, but with a stronger intensity in the superficial layer." (PMID 24979214, 2014). "In particular, we detected an increase of plasma cell HtrA1 immunostaining from gingivitis to chronic and aggressive periodontitis, with the higher intensity in aggressive disease." (PMID 24979214, 2014). "Gingivitis, chronic and aggressive periodontitis showed significantly higher levels of HtrA1 mRNA and protein expression respect to healthy tissues." (PMID 24979214, 2014). "Real-time PCR analysis of HtrA1 in chronic and aggressive periodontitis showed higher levels of mRNA expression than healthy tissues." (PMID 24979214, 2014). "In chronic and aggressive periodontitis plasma cells reactive to HtrA1 were more represented and strongly stained than in gingivitis, with an increasing intensity of the immunostaining from chronic to aggressive (p<0.001) periodontitis." (PMID 24979214, 2014). "Thus, the whole epithelium showed a significant increase of HtrA1 expression in chronic (p = 0.037) and aggressive (p<0.001) periodontitis compared to healthy subjects." (PMID 24979214, 2014). "Since deregulation of proteasome function is known to occur in various human diseases, HtrA1 proteolysis could be different among the analyzed periodontal pathologies." (PMID 24979214, 2014). "Interestingly, we found a greater amount of plasma cells positive to HtrA1 in the periodontitis lesions respect to gingivitis." (PMID 24979214, 2014). "In addition, aggressive periodontitis showed a more evident HtrA1 positivity in all layers than chronic periodontitis." (PMID 24979214, 2014). "In addition, we detected an increase of plasma cell HtrA1 immunostaining from gingivitis to chronic and aggressive periodontitis, with the higher intensity in aggressive disease." (PMID 24979214, 2014). "We suggest that the strong HtrA1 positivity observed in plasma cells of tissues from patients affected by chronic and aggressive periodontitis could reduce the inhibitory effects of TGF-β, allowing the increase of inflammatory mediators (TNF-α; IL-1β) promoting disease progression." (PMID 24979214, 2014). "The aim of this study was to examine, for the first time, the profile of HtrA1 protein and mRNA expression by immunohistochemistry and real-time PCR, respectively, in gingivitis and in generalized forms of chronic and aggressive periodontitis, compared to clinically healthy gingiva." (PMID 24979214, 2014). "The plasma cell expression of HtrA1 protein in periodontal diseases, high in chronic but stronger in aggressive periodontitis, could trigger the overproduction of matrix metalloproteinases, causing an increase in the MMP/TIMP-ratio in periodontal tissues with the resulting tissue destruction." (PMID 24979214, 2014).
periodontitis (continued). "Taken together, this study demonstrates C10-KR8 peptide regulate osteoimmunology and bone regeneration by Htra1/FAK/YAP pathway and that ZIF-8-based peptide loading platform is a promising strategy for periodontitis." (PMID 39076893, 2024). "This may show that HtrA1 gene expression is not a marker for a particular type of periodontitis but more probably for periodontal inflammation in general." (PMID 24979214, 2014).
rheumatoid arthritis (3 papers, 2017 to 2021). A chronic, systemic autoimmune disorder characterized by inflammation in the synovial membranes and articular surfaces. "Htra1 is upregulated in the synovial fluid and AC in patients with OA and rheumatoid arthritis and plays a critical role in disease development." (PMID 33916312, 2021). "Among serine proteases, Htra1 is upregulated in synovial fluid and articular cartilage in patients with OA and rheumatoid arthritis." (PMID 33430111, 2021).
serous ovarian carcinoma (3 papers, 2018 to 2024). "The reduced nuclear expression of HtrA1 is linked to a more favorable prognosis in patients with high-grade serous ovarian carcinoma." (PMID 38793064, 2024). "Altogether, our results demonstrate that nuclear downregulation of HtrA1 is associated with a better prognosis in women with high grade serous ovarian carcinoma." (PMID 30131069, 2018). "In conclusion, our results suggest that low nuclear expression of HtrA1 is associated with a lower risk of progression and death in women with high grade serous ovarian carcinoma." (PMID 30131069, 2018). "We evaluated the impact of HtrA1 downregulation in tumoral tissues on cancer progression and death in women with serous ovarian carcinoma." (PMID 30131069, 2018). "HtrA1 staining was performed on tissue microarrays (TMA) comprised of tumor samples from a cohort of 106 women who were diagnosed with primary high-grade serous ovarian carcinoma and receiving standard treatment at the Québec University Hospital between 1993 and 2006." (PMID 30131069, 2018).
small vessel stroke (3 papers, 2023 to 2025). "Additionally, HTRA1, of which lower genetically determined plasma levels were associated with extensive HIP-PVS, is encoded by a gene harboring both rare mutations causing monogenic cSVD21 and common variants associated with small vessel stroke and suggestively WMH20,22." (PMID 39011113, 2024).
type 2 diabetes (3 papers, 2023 to 2025). "Additionally, plasma levels of HTRA1 have been previously shown to associate with lower risk of type 2 diabetes." (PMID 38989470, 2024). "Consistent with effects of damaging variants in HTRA1, SGTB, and RBM12 acting independently of traditional cardiovascular risk factors, these associations persisted after adjusting for LDL cholesterol, smoking, type 2 diabetes, body mass index, and systolic blood pressure." (PMID 41190437, 2025).
arteriopathy (2 papers, 2024 to 2025). "Regarding the molecular pathogenesis of HTRAq1-related CSVD, in a murine HTRA1-deleted mouse model, HTRA1 deletion resulted in arteriopathy features, including intimal thickening, abnormal elastic lamina and vasodilation, along with reduced cerebral artery distensibility and blood flow." (PMID 38816814, 2024).
bladder cancer (2 papers, 2015 to 2020). "The single study of bladder cancer by Lorenzi and co-workers examined HtrA1 expression in tissue and urine from 152 subjects, 38 healthy individuals, 68 patients with urothelial cancer, and 16 subjects with cystitis, to establish a possible association with urothelial cancer." (PMID 26035313, 2015). "Down-regulation of HTRA1 in bladder cancer tissue regardless of grade and stage implicated that HTRA1 may act as a potential diagnostic biomarker of early stage." (PMID 32640634, 2020). "According to the Kaplan–Meier survival curves by different mRNA expression levels of hub genes of the bladder cancer with grade 3 carcinoma, GSN, PDLIM4, and HTRA1 were identified as prognostic genes (log-rank test: p = 5.796 × 10−5; log-rank test: p = 9.952 × 10−6; log-rank test: p = 0.009244)." (PMID 32640634, 2020).
Blindness (2 papers, 2016 to 2018). Blindness is the condition of lacking visual perception defined as a profound reduction in visual perception. "HtrA1 has been reported to be a crucial molecule in AMD, a leading cause of irreversible blindness in the elderly." (PMID 29695130, 2018).
breast tumors (2 papers, 2013 to 2015). "Additionally, we aimed at investigating for the presence of promoter hypermethylation as a mechanism for silencing the HTRA1 gene in breast tumors." (PMID 23580433, 2013). "Lehner and co-workers assessed the impact of HtrA1 mRNA expression on patient outcome in a cohort of 131 cancer patients using molecular and in vitro techniques to measure HtrA1 mRNA and HtrA1 promoter hypermethylation, the latter as an HtrA1 silencing mechanism in breast tumors." (PMID 26035313, 2015).
cardiomyopathies (2 papers, 2022 to 2023). "HTRA1 has been identified as part of a candidate gene signature correlated with cardiomyopathies in a gene correlation network analysis model and its mRNA expression is upregulated 6.9 fold in DCM." (PMID 36656640, 2023). "It is reasonable to consider that HTRA1 plays a significant role in the cardiomyopathy inflammation of DCM." (PMID 36547458, 2022). "Although the role of HTRA1 in DCM has not been reported, D Colak found HTRA1 significantly up-regulated (6.9-fold) in DCM and suggested that HTRA1 may contribute to cardiomyopathy pathways." (PMID 36547458, 2022).
corneal dystrophies (2 papers, 2019 to 2023). "In this study, the role of HtrA1 in the pathophysiology of TGFBI-linked corneal dystrophy was investigated by examining the ability of HtrA1 to cleave WT TGFBIp and seven mutants as well as WT FAS1-4 and six mutants." (PMID 31197037, 2019). "In summary, our results indicate that TGFBIp is an HtrA1 substrate and that some mutations in the gene encoding TGFBIp cause aberrant HtrA1-mediated processing that results in amyloidogenesis in corneal dystrophies." (PMID 31197037, 2019).